RN7SL796P (RNA, 7SL, cytoplasmic 796, pseudogene)
Gene: Miscellaneous RNA gene on chromosome 15 (30,560,644 to 30,560,934, forward strand). Ensembl gene ENSG00000277031.
Homologues: Orthologues: pig Metazoa_SRP (52% identical). Paralogues in human: RN7SL196P (99% identical), RN7SL286P (99% identical), RN7SL539P (99% identical), Metazoa_SRP (88% identical), RN7SL106P (88% identical), RN7SL238P (88% identical), RN7SL545P (88% identical), RN7SL759P (88% identical), RN7SL536P (87% identical), RN7SL185P (80% identical), RN7SL628P (79% identical), RN7SL82P (79% identical), and 700 more.